MRPL57 (mitochondrial ribosomal protein L57)
Synonyms: MRP63; mL63; bMRP63
Tractability: Small molecule: a structure with a bound ligand is known. PROTAC: its protein half-life has been measured.
Gene: Protein-coding gene on chromosome 13 (21,176,647 to 21,179,084, forward strand). Ensembl gene ENSG00000173141.
Subcellular location: Mitochondrion
Subcellular location (Human Protein Atlas): Mitochondria
Pathways (Reactome):
Metabolism of proteins: Mitochondrial ribosome-associated quality control; Mitochondrial translation elongation; Mitochondrial translation initiation; Mitochondrial translation termination
Gene Ontology:
Molecular function: protein binding; structural constituent of ribosome
Biological process: mitochondrial translation
Cellular component: mitochondrial large ribosomal subunit; mitochondrion; mitochondrial inner membrane; mitochondrial ribosome
Genetic constraint (gnomAD): Loss-of-function variants: 2 observed, 1.51 expected, observed/expected ratio (o/e) 1.32, 90% interval 0.43 to 1.91. That is too few expected variants to judge how well the gene tolerates losing a copy. Missense variants: 170 observed, 157.2 expected, observed/expected ratio (o/e) 1.08, 90% interval 0.95 to 1.23. Synonymous variants: 79 observed, 66.71 expected, observed/expected ratio (o/e) 1.18, 90% interval 0.99 to 1.43.
Homologues: Orthologues: chimpanzee MRPL57 (99% identical), macaque MRPL57 (97% identical), rat Mrpl57 (84% identical), mouse Mrpl57 (83% identical), dog MRPL57 (81% identical), guinea pig MRPL57 (81% identical), pig MRPL57 (74% identical), tropical clawed frog mrpl57 (63% identical), zebrafish mrpl57 (62% identical).